MSLN (mesothelin)
Diseases named in the same sentence as MSLN in open-access papers (continued):
Sharing a sentence is not in itself a finding about the gene and the disease.
tumor (656 papers, 2005 to 2026). "Tumor-associated antigens like MSLN, CEA, EGFR, ROR1, and c-Met are overexpressed in many solid tumors but often show low-level expression in normal tissues." (PMID 40969260, 2025). "Transcriptionally, all 16 cell lines express various levels of other tumor-associated antigens, such as mesothelin, survivin, folate receptor and Erbb2." (PMID 40642792, 2025). "CA125 interacts with specific ligands, including galectin-1/3, mesothelin, and Siglec-9, which play key roles in regulating tumorigenesis, progression, migration, invasion, and tumor immunity through various signaling pathways associated with cancer." (PMID 40458729, 2025). "CAR T‐cell therapies for PM have primarily targeted several specific tumor‐associated antigens, including MSLN, placental alkaline phosphatase‐like 2 (ALPPL2), fibroblast activation protein (FAP), and MET." (PMID 40904706, 2025). "Mesothelin, frequently overexpressed in biliary cancers, is implicated in tumor progression through its role in cell adhesion, migration, and immune evasion." (PMID 40013133, 2025). "The limited availability of true tumor-specific antigens (TSAs) and the frequent antigen-loss escape seen with tumor-associated antigens (e.g., mesothelin) constrain single-target CAR-T efficacy." (PMID 41281758, 2025). "For instance, the tumour cell subcluster GC_P02T exhibited a high expression of MSLN, a cancer-associated antigen which is upregulated in various malignant tumours, including GC." (PMID 39877290, 2025). "In high-grade serous ovarian carcinoma, tumor-associated mesothelin activates Wnt/β-catenin signaling, subsequently upregulating CD24 expression." (PMID 41417432, 2025). "As mesothelin (MSLN) is a tumor-associated antigen overexpressed in PDAC, we evaluated the effect of MSLN nanovaccine in a syngeneic orthotopic KPC-PDAC mouse model." (PMID 40266223, 2025). "MSLN is a biomarker associated with tumor dissemination, cellular migration, and proliferation, and it can be used to evaluate the effect of GAL treatment in OC cell lines." (PMID 41462867, 2025). "Over the past decades, many studies have highlighted a link between MSLN and cancer progression and its association with specific features within the tumor microenvironment (TME)." (PMID 41335396, 2025). "As organoids are derived from the tumor’s progenitor population, our data suggest that MSLN is associated with the stemness compartment driving tumor growth." (PMID 40402266, 2025). "The heterogeneous expression of MSLN and its loss over time, along with the immunosuppressive tumor microenvironment (TME), are key factors restricting effectiveness." (PMID 40366419, 2025). "Analysis of clinical samples revealed a significant increase in MSLN expression levels in tumor tissues associated with brain metastasis, which correlates closely with a shortened survival period for patients." (PMID 41400642, 2025). "Despite formidable barriers, several tumor-associated antigens—such as mesothelin (MSLN), prostate stem cell antigen (PSCA), carcinoembryonic antigen (CEA), HER2, MUC1, and CD133—are being explored as targets." (PMID 40700298, 2025). "High MSLN expression is reportedly associated with poor outcomes, reduced overall survival, tumor dissemination, and increased cellular migration, making it a potential biomarker for evaluating the efficacy of specific treatments." (PMID 41462867, 2025). "In the context of MSLN-targeted therapies, bsAbs have been engineered to simultaneously bind a tumor-associated antigen, such as MSLN, and a co-stimulatory receptor expressed on T-cells (e.g., CD3, CD20, CD47, CD137)." (PMID 41335396, 2025). "Through a side-by-side comparison of MSLN-specific VHH CARs with affinities spanning from subnanomolar to micromolar KD, we examined the risk of fatal on-target, off-tumor toxicity associated with high-affinity MSLN CARs." (PMID 39576012, 2024).
tumor (continued). "Out of surface targets, mesothelin is one of the most studied cancer-associated antigens overexpressed on the membrane of PM cells, which seems to have a role in tumour development, metastasis and drug resistance." (PMID 39329996, 2024). "Amongst the identified cancer antigens of KRAS-mutated PDAC, CEA and MSLN were reported to be overexpressed and promoted tumor progression PDAC." (PMID 39453574, 2024). "Our preclinical studies demonstrated that high-affinity MSLN CARs were associated with fatal on-target, off-tumor toxicity and that affinity-tuned CARs rendered T cells more selective for MSLN-high tumors." (PMID 39576012, 2024). "In the present study, we utilized our phage display libraries to isolate a TCR that binds in an HLA-independent manner directly to the tumor-associated antigen mesothelin." (PMID 38574067, 2024). "Due to this relationship, it can be posited that this increase in MSLN gene expression also plays a role in the associated features of these molecular subtypes and tumor location." (PMID 39174744, 2024). "Testing of this HiT in cellular assays has demonstrated that it can bind to mesothelin displayed on the surface of target tumor cells and cause activation of the T cell, leading to cytotoxicity." (PMID 38574067, 2024). "We established a tumor model by subcutaneous injection of luciferase-encoding HeLa cells, which expressed high levels of mesothelin." (PMID 38440217, 2024). "We designed a TriKE molecule targeting mesothelin to overcome the immunosuppressive tumor environment implicated by circulating immune cells in NSCLC patients." (PMID 36911670, 2023). "The binding of mesothelin to the tumor-associated cancer antigen 125 (CA-125) can lead to heterotypic cell adhesion and tumor metastasis within the pleural and peritoneal cavities." (PMID 36968141, 2023). "This suggests that MSLN surface expression in control mice gradually decreased during tumor progression, whereas MSLN-CAR therapy accelerated the loss of MSLN surface expression." (PMID 36746513, 2023). "Conversely, low expression of MSLN by tumor cells was associated with tumor necrosis and nuclear grade." (PMID 37901248, 2023). "A significant association was found between high MSLN expression by tumor cells and high density of collagen type I fibers in the TME (P = 0.005)." (PMID 37901248, 2023). "The results showed that high expression of MSLN by tumor cells was associated with diffuse expression of D2-40 (P = 0.009)." (PMID 37901248, 2023). "Next, we evaluated the association between tumor cell MSLN expression and histological biomarkers of tumor aggressiveness." (PMID 37901248, 2023). "CAR T cell therapies that target tumor-associated antigens, such as mesothelin and folate receptor alpha, have shown encouraging outcomes in early-phase clinical trials." (PMID 38075052, 2023). "Next, we examined the association of MSLN expression by tumor cells with PD-L1 expression and the density of immune cells in the tumor microenvironment (TME)." (PMID 37901248, 2023). "Higher EMT/tumor/CSC marker abundance was significantly associated with the carboplatin responder group including protein markers Mesothelin, Nanog, STAT1, and E-Cadherin." (PMID 35740561, 2022). "This study evaluated the potential risk of “on-target off-tumor” toxicity for different human organs in anti-MSLN CAR T cell therapy by single-cell RNA-seq data analysis." (PMID 36059490, 2022). "Previous studies from our and other groups indicate that MSLN OE is associated with improved cell survival and invasiveness, increased tumor burden and peritoneal dissemination, as well as poor prognosis in OC patients." (PMID 35162954, 2022). "Not only this but also the presence of MSLN in BC cells is associated with tumor infiltration of the lymph node." (PMID 36387279, 2022). "MSLN was selected as a target tumor antigen based on its association with poor prognosis and overexpression in various solid cancers." (PMID 36059490, 2022).
tumor (continued). "The aim of this study is to investigate the interlinkage between MALAT1 and HOTAIR and their regulatory activity on immunomodulation by examining the expression profile of CD80 and MSLN in tumor-associated macrophages in the hormonal, HER2+, and TNBC subtypes." (PMID 36387279, 2022). "In patients with early-stage lung adenocarcinoma, mesothelin overexpression is significantly associated with tumor aggressiveness and a lower survival rate." (PMID 36153626, 2022). "CRS-207 is a bacterial based vaccine of attenuated Listeria monocytogenes which was modified to express mesothelin (MSLN)—A tumour associated antigen (cell-surface glycoprotein) expressed in PDAC." (PMID 33546207, 2021). "When a human PC cell line (Mia-MSLN) with high expression of MSLN was orthotopically injected into the pancreas of the immune-deficient mouse, the cells proliferated and formed the tumor tissues." (PMID 34577541, 2021). "Human mesothelin (MSLN) is a tumor associated antigen overexpressed in several aggressive, poor prognosis, and orphan-drug tumors." (PMID 33418877, 2021). "The success of this combinatorial setting was proposed to be caused by a GVAX-induced expansion of mesothelin-specific CD8+ T cells within the tumor microenvironment, thereby enhancing the efficacy of the anti-CTLA-4 antibody treatment." (PMID 33710604, 2021). "MSLN has been the focus of immunotherapy research since its discovery as a promising therapeutic target for reducing risk of ‘on-target/off-tumor’ toxicities due to its expression profile in normal and cancer tissue." (PMID 34439085, 2021). "MSLN has been implicated in key tumorigenic roles such as MPM tumor growth, metastasis, and drug resistance, but its exact mechanisms are poorly understood." (PMID 34439085, 2021). "Mesothelin (MSLN) is implicated in tumour invasion and is widely overexpressed in solid tumours, including PDAC." (PMID 33008426, 2020). "Overexpressed differentiation antigens, such as mesothelin, or components of the tumour-associated stroma, such as fibroblasts or endothelial cells, represent attractive targets for chimeric antigen receptor T cell therapy." (PMID 32156681, 2020). "Studies showed that MSLN expression is associated with tumor burden, increasing cancer stage, and poor overall survival (OS)." (PMID 32983962, 2020). "MSLN overexpression has been reported to be associated with a strongly invasive and aggressive tumor phenotype in TNBC." (PMID 31354732, 2019). "The overexpression of MSLN and mucins in many adenocarcinomas has been implicated in cell adherence, cell survival/proliferation, tumor progression, and chemo-resistance." (PMID 31222072, 2019). "One study showed that a cell-based vaccine, Meso-VAX, in combination with the adeno-associated virus (AAV)-IL-12 increased the number of MSLN-specific T cells and the levels of anti-MSLN Abs and enhanced tumor clearance activity in mice." (PMID 31463062, 2019). "An increase in tumor burden and poor overall survival are associated with elevated MSLN expression according to clinical observations." (PMID 31463062, 2019). "An association between MSLN expression, tumor invasion and matrix metalloproteinases activation has been demonstrated in vitro, in vivo, and in patients with malignant pleural mesothelioma." (PMID 31354732, 2019). "MORAb-009 is a chimeric antimesothelin monoclonal antibody that was utilized to target tumor-associated mesothelin overexpressed on pancreatic, ovarian, lung, and colorectal carcinoma." (PMID 29707526, 2018). "Here, we report the engineering of Fn3 variants that bind with high affinity to the MSLN tumor cell surface protein, beginning with the naïve fibronectin YSD Gr2 library." (PMID 29738555, 2018). "Soluble Fn3 variants demonstrated high-affinity binding to tumor cells positive for MSLN expression, and were internalized into tumor cells upon binding." (PMID 29738555, 2018).
tumor (continued). "We established a tumor cell binding assay to measure the binding affinities of soluble engineered Fn3 variants for MSLN-expressing cancer cells." (PMID 29738555, 2018). "Mesothelin overexpression promotes tumor cell proliferation and regional invasion and is associated with poor prognosis, such as worse recurrence-free survival (RFS) and overall survival (OS)." (PMID 28356156, 2017). "Human antibodies specific to several tumor targets were used in that study, including anti-mesothelin and MN-antigen (a tumor associated antigen carbonic anhydrase IX, CA9)." (PMID 28574434, 2017). "In our current study, we characterized a tumor-targeted variant of TR3 by harnessing the strong binding affinity of the two well described biomarkers mesothelin and MUC16." (PMID 24447304, 2014). "Our findings indicate that tumor-released mesothelin is linked to GPI anchor, engages macrophage mannose receptor, and contributes to macrophage polarization towards TAMs." (PMID 22163010, 2011). "The correlation of mesothelin expression with several other clinicopathological features, including pathological stage, tumour grade, drug resistance status, and status of optimal surgery, indicates that mesothelin seems to be associated with these variables." (PMID 19293794, 2009). "Serum mesothelin levels are elevated in MM, suggesting a role in early diagnosis of this tumor in high-risk populations, a role as marker for monitoring treatment response, and a potential target for tumor-related therapy." (PMID 19662202, 2007). "Basal expression of MSLN can become a major issue, as therapeutics may be redirected to healthy tissues, causing off-target/off-tumor toxicity." (PMID 41335396, 2025). "Multi-target designs can reduce tumor escape risk by targeting MSLN and co-expressed tumor antigens; combining strategies such as oncolytic viruses or cancer vaccines, or low-dose immune checkpoint inhibitors to modulate the tumor microenvironment, can further enhance therapeutic efficacy." (PMID 41400642, 2025). "Moreover, MSLN can stimulate tumor-associated macrophages through paracrine mechanisms, leading to the secretion of significant amounts of cytokines such as VEGFA and S100A9." (PMID 41400642, 2025). "Indeed, sMSLN acts as a decoy for MSLN-targeted therapeutics, reducing therapeutic efficacy or causing off-tumor toxicity in patients." (PMID 41335396, 2025). "Studies have found that high MSLN expression is associated with the epithelioid PM subtype and a high density of CD8+ T cells, CD68+ macrophages, and type I collagen fibers, whereas low MSLN expression is linked to tumor necrosis and nuclear Grade 1 (low malignancy)." (PMID 40904706, 2025). "Although the significant role of MSLN in tumor growth and metastasis has been widely recognized, whether MSLN can serve as a reliable tumor diagnostic marker or an independent prognostic indicator remains controversial." (PMID 41400642, 2025). "MSLN is closely associated with enhanced tumor cell proliferation." (PMID 41400642, 2025). "In principle, these antibodies may target tumor-associated antigens such as MUC1 or mesothelin, patient-specific neoantigens, or even self-antigens, as reported in other cancers." (PMID 41008793, 2025). "Together, these findings underscore the potential risks associated with high-affinity CARs targeting MSLN, which may cause unpredictable on-target, off-tumor toxicities and could be responsible for the adverse events observed in clinical trials." (PMID 39576012, 2024). "Additionally, aberrant expression of MSLN has been associated with tumor aggressiveness, malignant transformation, increased invasion and metastasis, and resistance to apoptosis." (PMID 39576012, 2024). "MPM is strongly responsive to synthetic activators of cGAS/STING pathway that increase the production of CXCR3 in tumor cells and cancer-associated fibroblasts, resulting in the recruitment and activation of NK cells and mesothelin-targeted chimeric antigen receptor (CAR)-NK cells." (PMID 39709435, 2024).
tumor (continued). "Tumor mesothelin expression associated with the TME immune landscape predicts the risk of death for patients with MPM and could be a new target for immunotherapy in MPM." (PMID 37901248, 2023). "Low MSLN expression was associated with tumor necrosis (P = 0.03) and nuclear grade 1 (P = 0.007)." (PMID 37901248, 2023). "The association between increased MSLN expression in tumor cells and increased collagen type I fibers suggests that this protein could be involved in maintaining the plasticity of the TME to avoid invasion by malignant cells." (PMID 37901248, 2023). "Although its exact function is unknown, mesothelin is associated with cancer cell adhesion, tumor progression, survival, proliferation, and resistance to apoptosis." (PMID 38067366, 2023). "MSLN was originally identified by Pastan and colleagues as a tumour-associated antigen due to its limited expression by normal tissues and overexpression on tumours." (PMID 36166071, 2023). "High MSLN expression was found in heart, lung and stomach, indicating that these organs could be at high risk of “on-target off-tumor” toxicity for anti-MSLN CAR T cell therapy." (PMID 36059490, 2022). "The scRNA-seq data from respiratory system tissues indicated that pulmonary cells contained approximately 2.40% MSLN-positive cells, so the lung could be at high risk of “on-target off-tumor” toxicity for MSLN-CAR-T cell therapy." (PMID 36059490, 2022). "We evaluated the association between MSLN expression in primary tumours and survival." (PMID 36434635, 2022). "This showed that 7.71% of myocardial cells expressed MSLN, indicating that there may be a high risk of “on-target off-tumor” toxicity in the heart for MSLN-CAR-T cell therapy." (PMID 36059490, 2022). "We demonstrated that the in vivo treatments with the optimized ADCs resulted in almost complete eradication of the xenograft tumors at the treatment endpoints, without detectable off-target toxicity because of the ADCs’ high specificity targeting the cell surface tumor-associated MSLN." (PMID 34326410, 2021). "Historically high expression of MSLN was linked to increased tumor proliferation/invasion." (PMID 34966784, 2021). "Nevertheless, the high expression of mesothelin by cancer cells and its low expression on normal tissue made this protein an ideal tumor-associated antigen, and led to development of several anti-mesothelin targeted agents, including mAbs, vaccines, immunotoxins and lastly antibody–drug conjugates." (PMID 33509252, 2021). "However, mesothelin is also expressed on normal tissue at low levels, it is a tumor-associated antigen (TAA)." (PMID 33777013, 2021). "When human OvCa cell lines were genetically engineered to have a gain of function to MSLN, there was an increase in tumor cell survival and invasion both in vitro and in vivo and the opposite was observed in loss of function cells suggesting the importance of MSLN expression in tumor cells." (PMID 34830322, 2021). "The diagnostic value of circulating mesothelin has been also suggested in those neoplasms." (PMID 31035965, 2019). "An ineffective anti-tumor immune response may also be caused by the shedding of mesothelin by the tumor in vivo (decoy mesothelin) blocking the immune effector antibodies and T cells." (PMID 29474384, 2018). "Mesothelin (MSLN) is a glycophosphatidylinositol (GPI)-linked cell surface protein highly expressed in several types of malignant tumors sometimes in association with increased tumor aggressiveness and poor clinical outcome." (PMID 28460459, 2017). "In addition, mesothelin overexpression reliably caused a decrease in a heterotopic tumor growth in an immunocompetent syngeneic mouse model, when compared to wild type or stable vector transfected/transduced Panc02 lines." (PMID 26931187, 2016). "It was thus unclear whether soluble mesothelin remains linked to the GPI anchor in patient fluids or in tumor-conditioned media." (PMID 22163010, 2011).